LIF (LIF interleukin 6 family cytokine)
Diseases named in the same sentence as LIF in open-access papers (continued):
Sharing a sentence is not in itself a finding about the gene and the disease.
autoimmune disease (6 papers, 2013 to 2022). A disorder resulting from loss of function or tissue destruction of an organ or multiple organs, arising from humoral or cellular immune responses of the individual to their own tissue constituents. "LIF is a cytokine that has the potential to limit demyelination and oligodendrocyte loss in CNS autoimmune diseases and to affect the T-cell mediated autoimmune response." (PMID 23700462, 2013). "Overall, the current findings suggest that hADSCs overexpress the effects of IFNβ and LIF on the treatment of autoimmune diseases of the CNS." (PMID 36284106, 2022). "LIF is a pleiotropic cytokine that promotes neurogenesis in fetus cerebrum and autoimmune diseases treatment." (PMID 33891593, 2021). "It has been widely reported in the literature that many cytokine and chemokine genes (e.g., TNF-a, IL-8, CXCL2, CXCL3, CXCL10, LIF, IL-17C and IL-23A) are the basis of autoimmune disorder pathways that are characterized by inflammation." (PMID 28099447, 2017).
cardiac hypertrophy (6 papers, 2011 to 2025). "Constitutively activated Cdc42 enhances cardiomyocyte hypertrophy, and downregulated or inhibited Cdc42 activity attenuates LIF-induced cardiomyocyte elongation or high salt-induced cardiac hypertrophy and fibrosis." (PMID 40610735, 2025). "Additionally, Wang F and colleagues found that hemodynamic overload can increase LIF expression in the heart, thereby protecting the heart from failure by blocking apoptosis and stimulating cardiac hypertrophy." (PMID 39726944, 2024). "Antisense ODNs directed against leukemia inhibitory factor (LIF) and cardiotrophin-1 were successful in downregulating angiotensin II-induced cardiac hypertrophy in vitro." (PMID 34089101, 2021). "The activated MEK5/ERK5 signaling pathway by IL-6 family cytokines, leukemia inhibitory factor (LIF) and carddiotrophin-1 (CT-1) has been shown to result in the serial assembly of sarcomeres and eccentric cardiac hypertrophy." (PMID 21792366, 2011). "Moreover, our lab observed that chronic treatment of mice with the IL-6 family cytokine, leukemia inhibitory factor (LIF) did not induce cardiac hypertrophy." (PMID 30619368, 2018). "Conversely, adenovirus-mediated overexpression of SOCS3 in cardiomyocytes markedly inhibits the LIF and CT-1-induced hypertrophic response, as well as activation of gp130 downstream signals, suggesting that SOCS3 may be a new potential therapeutic target for treatment of cardiac hypertrophy and HF." (PMID 33585485, 2021).
Miscarriage (6 papers, 2012 to 2025). A pregnancy that ends at a stage in which the fetus is incapable of surviving on its own, defined as the spontaneous loss of a fetus before the 22th week of pregnancy. "The reduction in uterine expression of kisspeptin is associated with implantation failures and miscarriage, as well as reduced uterine levels of LIF, supporting the findings of reduced LIF expression in the present study." (PMID 39859259, 2025). "Because a low level of LIF is associated with unexplained miscarriages and RIF in humans, it can be hypothesized that GH can partly compensate for LIF insufficiency." (PMID 36142268, 2022). "In the middle luteal phase, LIF expression in the endometrium of patients with recurrent miscarriage was significantly reduced when compared with healthy child-bearing females." (PMID 23226768, 2012).
Sepsis (6 papers, 2019 to 2023). Sepsis is defined as life-threatening organ dysfunction caused by a dysregulated host response to infection. "Pituitary gene expression levels of pro-inflammatory cytokines TNF-α and LIF were higher than normal, but only in the acute phase of sepsis-induced critical illness (1-day sepsis group) and this by more than sevenfold and eightfold, respectively." (PMID 33593393, 2021). "Circulating LIF levels are elevated in patients with sepsis and septic shock, with levels being correlated with the severity of disease." (PMID 34074039, 2021). "Pituitary gene expression of LIF was even lower than normal during the subacute phase of sepsis-induced critical illness (3-day and 5-day sepsis groups)." (PMID 33593393, 2021). "Previous studies have demonstrated that circulating LIF levels are correlated with the severity of sepsis in humans." (PMID 34074039, 2021). "In the animal model, administering LIF reduces the severity of sepsis and recruitment of neutrophils in bacterial infections." (PMID 34074039, 2021). "Therefore, endogenous LIF attenuates sepsis and septic shock and downregulates tumor necrosis factor-α synthesis and release in LPS-induced sepsis mice." (PMID 34074039, 2021). "Furthermore, endogenous LIF attenuates acute inflammatory responses and downregulates TNFα synthesis in LPS-induced sepsis mice." (PMID 34074039, 2021). "Our study demonstrated that iPSC-CM promoted endogenous LIF to inhibit neutrophils TEM and attenuate the severity of sepsis-induced ALI." (PMID 34074039, 2021). "Comparison of molecules between the control and sepsis groups revealed statistically significant differences, except for IFN-α, IL-1RA, IL-1β, IL-2, IL-6, IL-7, IL-15, LIF, GM-CSF, TNF-α, CCL4, CCL5, and CXCL12." (PMID 31583025, 2019).
atherosclerosis (5 papers, 2019 to 2025). A disease characterized by the build-up of fatty material and calcium deposition in the arterial wall resulting in partial or complete occlusion of the arterial lumen. "Interestingly, both LIF and cathepsin L have been implicated in the development and progression of vascular diseases such as abdominal aortic aneurysm and atherosclerosis." (PMID 34779136, 2022). "Data have demonstrated that LIF is effective in not only inhibiting the formation of plaque but also retarding the progression of pre-existing atherosclerotic plaques in atherosclerosis." (PMID 33589571, 2021). "Of note, LIF, a pleiotropic cytokine, has been proven to be anti-inflammatory, and increases IL10 expression, which can ameliorate atherosclerosis." (PMID 33589571, 2021). "In more detail, leukemia inhibitory factor (LIF), a multifunctional cytokine of the IL-6 superfamily, plays an important role in host immunity and contributes to atheroma formation, consistent with findings that inhibition of LIF reduces atherosclerosis." (PMID 40698076, 2025).
colitis (5 papers, 2019 to 2023). Inflammation of the colon. "In contrast, in plasma, colitis-induced increases in interleukin (IL)-2, leukemia inhibitory factor (LIF), monocyte chemoattractant protein (MCP)-1, and tumor necrosis factor (TNF) were reduced in animals with an A allele." (PMID 34916909, 2021). "Results from this study and our study revealed important functions of LIF in the gut under different conditions, including physiological conditions, injury induced by IR, and colitis conditions, through different mechanisms." (PMID 32719388, 2020). "LIF protects colitis through regulating the function of lamina propria lymphocytes via the STAT4 signaling and repair function of IECs via the STAT3/YAP signaling." (PMID 32719388, 2020). "A recent study reported that LIF plays a protective role in mouse experimental colitis models." (PMID 32719388, 2020). "Under the colitis condition, microbiota dysregulation induces LIF secretion by IECs." (PMID 32719388, 2020). "We found that there were 15 analytes upregulated in both DSS and C. rodentium colitis, including innate immune cell-associated cytokines (G-CSF, IL-1β, TNF-α, LIF, and IL-6), chemokines (CCL2, CCL5, CCL11, CXCL2, CXCL8, CXCL9, MIP-1α, and MIP-1β), and Th1 (IFN-γ) and Th17 (IL-17) cytokines." (PMID 30972302, 2019). "For IL-2 and LIF, inflammation-induced increases were reversed with an A genotype, whereas for MCP-1 and TNF, colitis-induced increases were attenuated with an A genotype." (PMID 34916909, 2021). "Many of the colitis-induced cytokines that we found to be influenced by the FAAH SNP (e.g., IL-2, LIF, MCP-1, and TNF), have been found to be regulated by FAAH inhibition in other studies." (PMID 34916909, 2021). "Moreover, a recent study found that leukemia inhibitory factor (LIF), a cytokine in the IL-6 family secreted by IECs, alleviates colonic inflammation by inhibiting the differentiation of Th17 cells in a mouse model of colitis." (PMID 36590401, 2022).
embryonal carcinoma (5 papers, 2011 to 2022). A non-seminomatous malignant germ cell tumor characterized by the presence of large germ cells with abundant cytoplasm resembling epithelial cells, geographic necrosis, high mitotic activity, and pseudoglandular and pseudopapillary structures formation. "For instance, embryonal carcinoma (EC) cells, ESCs cultured in serum or serum/LIF, iPSCs, CiPSCs, RSCs, and XPSCs express high levels of naïve GRN-like genes and might also be regarded as ‘naïve’ ESCs." (PMID 35390160, 2022). "In vitro, Oct4 is found in ES cells and embryonal carcinoma (EC) cells and is down-regulated when these cells are induced to differentiate with retinoic acid (RA) treatment or by removing leukemia inhibitory factor (LIF)." (PMID 26769970, 2016).
fibroids (5 papers, 2015 to 2024). "Many proteins such as F3, WNT2, CDH1, and LIF shown in the protein–protein interaction networks are well known in leiomyoma pathogenesis, and others, such as ICAM1, CXCL8, CCL2, and NANOG are novel and require further investigation." (PMID 36835153, 2023). "A similar study was performed evaluating the expression of LIF using quantitative RT-PCR in patients with abnormal uterine cavities (submucosal fibroids and polyps) and control patients." (PMID 28620517, 2015). "It is worth noting that LIF expression is decreased in the endometria of women with fibroids, and since LIF can influence various cellular processes, including adhesion, through signaling pathways such as the JAK/STAT pathway, further research is needed to clarify this relationship." (PMID 39338174, 2024).
inflammatory bowel disease (5 papers, 2014 to 2025). A spectrum of small and large bowel inflammatory diseases of unknown etiology. "rs713875 is a C/G variant located downstream of the HORMAD2 and LIF genes that has been implicated in multiple diseases, including Crohn's disease, IgA nephropathy and early-onset inflammatory bowel disease." (PMID 24911414, 2014). "Furthermore, LIF acts as an important immunomodulator and demonstrates protective effects in various immunopathological conditions such as infections, inflammatory bowel disease (IBD), multiple sclerosis and GVHD." (PMID 40943537, 2025). "In laminar propria lymphocytes of inflammatory bowel disease patients, LIF-activated STAT4 inhibits activation of the STAT3-dependent Il17a/Il17f promoter, while in intestinal epithelial cells, LIF bypasses abnormally low STAT4 levels and induces YAP gene expression by activating STAT3." (PMID 33505963, 2020). "The inflammation and inflammatory bowel disease (IBD) disorders had many commonly modulated genes that were also found in the String analysis that were common with the disorders which included IL-8, ICAM1, RELB, NFκBIA, TNFAIP3, LIF, CXCL1, CXCL2, CXCL3, CXCL10, and TNF-α." (PMID 28099447, 2017).
medulloblastoma (5 papers, 2011 to 2022). A malignant, invasive embryonal neoplasm arising from the cerebellum. "Multiple factors have been identified as STAT3 signaling promoters, including IL-6 and LIF which are over expressed in medulloblastomas." (PMID 28035977, 2016). "LIF has been shown to be constitutively expressed in medulloblastoma cells and we found high levels of LIF secreted in UW288-1 and UW426 cells." (PMID 21526200, 2011). "Moreover, the observation that medulloblastoma cell lines generally express LIF confirms the presence of an autocrine loop in this malignant brain tumor." (PMID 25915540, 2015). "In order to investigate whether the LIFRα is functional in medulloblastoma cell lines, we analyzed the activation status of downstream signaling pathways in response to cell stimulation with LIF." (PMID 25915540, 2015). "Nevertheless, we found that LIF was up-regulated in resveratrol-treated medulloblastoma cells with STAT3 inactivation presumably due to the feedback loop of STAT3 and LIF in those cells." (PMID 28035977, 2016). "We also wanted to examine the secretion of leukemia inhibitory factor (LIF) because it is an IL-6 family member that has been shown to be constitutively expressed both in vitro and in vivo in medulloblastoma cells." (PMID 21526200, 2011).
metastatic tumors (5 papers, 2014 to 2023). "Other baseline circulating miRNAs such as miR-143-3p, miR-197-3p, miR-223-3p, miR-223-5p, miR-338-3p, and miR-652-3p, as well as plasma LIF levels, are significantly higher in patients who develop secondary metastatic disease." (PMID 37759086, 2023). "Interestingly, LIF expression levels exhibited a similar pattern, showing very high levels of expression in benign tumors, with a progressive decrease in malignant and metastatic tumors." (PMID 25885043, 2015). "Ectopic LIF expression in MCF7, T47D and MDA-MB-231 cells significantly increased the number of lung metastatic tumors." (PMID 24553191, 2014). "Immunohistochemical results exhibited strong immunoreactivity of cytoplasmic LIF in primary tumors obtained from NPC patients diagnosed with local recurrence or distal metastasis, which was even stronger in metastatic tumor lesions, particularly those metastasizing to liver or lung (right)." (PMID 30504771, 2018).
preeclampsia (5 papers, 2015 to 2025). Preeclampsia is a hypertensive disorder of pregnancy that is characterized by new-onset hypertension with proteinuria presenting after 20 weeks of gestation, and depending on mild or severe forms may initially present with severe headache, visual disturbances, and hyperreflexia. "Therefore, understanding the link between LIF and the pathogenic mechanisms of preeclampsia may contribute to the development of effective treatments for preeclampsia." (PMID 38235138, 2023). "Further specific research is needed to determine whether the increase in EGF, HGF, LIF and SCF is a consequence of preeclampsia or if it indicates changes in factors associated with preeclampsia." (PMID 41006365, 2025). "This evidence supports the elevation of LIF observed in preeclampsia in our study." (PMID 41006365, 2025). "At term, placental LIF is elevated in women with preeclampsia." (PMID 26479247, 2015). "EGF, HGF and LIF and SCF levels were significantly elevated in preeclampsia." (PMID 41006365, 2025). "In conclusion, we confirmed an increase in EGF, HGF, LIF and SCF in preeclampsia." (PMID 41006365, 2025). "The JAK/STAT3 pathway works closely with leukemia inhibitory factor (LIF) to induce inflammation and endothelial dysfunction, characterized by increased levels of intercellular adhesion molecule-1 (ICAM-1) and vascular cell adhesion molecule-1 (VCAM-1), all of which are hallmarks of preeclampsia." (PMID 39596234, 2024).
rhabdomyosarcoma (5 papers, 2015 to 2022). A rare aggressive malignant mesenchymal neoplasm arising from skeletal muscle. "LIF expression within rhabdomyosarcoma cells increased cell adhesion and stimulated F-actin bundle formation and colocalization with FAK and paxillin in filopodia." (PMID 35204717, 2022). "Another cancer that typically metastasizes to bone is rhabdomyosarcoma, mouse models of rhabdomyosarcoma identified LIF expression within the bone marrow as a chemoattractant for rhabdomyosarcoma cells, and treatment with siRNA against LIFR was able to decrease bone metastasis." (PMID 35204717, 2022). "LIF has been identified as a metastatic factor in rhabdomyosarcomas." (PMID 28952053, 2018).
ZIKV infection (5 papers, 2018 to 2022). "We found that PTBP1, LIF, GHR, and PTBP3 were upregulated while EDNRB and MBP were downregulated upon ZIKV infection." (PMID 33891593, 2021). "Our results showed that mRNA levels of PTBP1, LIF, PTBP3, and GHR were significantly upregulated, while EDNRB and MBP were downregulated upon ZIKV infection at indicated time." (PMID 33891593, 2021). "Among the top selected differentially expressed genes, such as PTBP1, LIF, GHR, PTBP3, EDNRB, and MBP, the mRNA and protein expressions were confirmed to identify the dysregulation of the transcriptome in MPAs upon ZIKV infection." (PMID 33891593, 2021). "Notably, we detected the downregulation of two genes, Leukemia Inhibitory Factor (LIF) and Poliovirus Receptor (PVR), related to other viruses yet not currently linked to ZIKV infection." (PMID 35304593, 2022).
acute kidney injury (4 papers, 2019 to 2025). Sudden and sustained deterioration of the kidney function characterized by decreased glomerular filtration rate, increased serum creatinine or oliguria. "Previous studies have shown that LIF acts as a protective factor against ischemic acute kidney injury and is involved in renal epithelial regeneration following AKI." (PMID 41347022, 2025). "At the kidney level, LIF regulates nephrogenesis protecting from oxidative stress and promoting tubular regeneration after acute renal failure." (PMID 36287942, 2022). "A recent study shows that LIF promotes tubular regeneration after acute renal failure." (PMID 33922243, 2021). "As LIF has a role in nephrogenesis, it was hypothesised that LIF could participate in renal regeneration following acute kidney injury." (PMID 30871285, 2019).
Anorexia (4 papers, 2017 to 2026). Lack of desire to eat (loss of appetite). "Anorexia can be caused by elevated LIF expression, which, according to different studies, decreases food intake and leads to weight loss." (PMID 35740622, 2022). "At a very early stage, LIF can increase leptin, leading to anorexia and weight loss, but due to adaptive changes in the body, the effects of LIF are disturbed, leptin expression is suppressed, and anorexic behavior is ameliorated." (PMID 35740622, 2022). "Animal experiments have shown that LPS can lead to the up-regulation of LIF expression in the central nervous system, resulting in extensive inflammation and anorexia, and with the combination of LPS and corticosterone, LIF up-regulation is more prominent." (PMID 35740622, 2022). "It is worth noting that there seems to be a consensus that the activation of IL-6 expression follows the up-regulated expression of LIF, thereby promoting the occurrence of anorexia and cachexia syndrome in tumor patients." (PMID 35740622, 2022). "It was shown that LIF could promote the expression of leptin at an early stage and generate anorexia." (PMID 35740622, 2022). "However, in the later stages of LIF-induced anorexia, food intake returns to basal levels as serum and adipose leptin expression decreases and hypothalamic STAT3 phosphorylation activation is reduced." (PMID 35740622, 2022). "We speculate that anorexia induced by abnormally high LIF expression may be an acute response." (PMID 35740622, 2022). "Current research has confirmed that LIFR is expressed in proopiomelanocortin (POMC) neurons in the arcuate nucleus (ARC) region in the hypothalamus, which can be activated by LIF and then α-MSH released from ARC POMC neurons to induce anorexia." (PMID 35740622, 2022).
astrocytoma (4 papers, 2007 to 2024). "The induction of LIF, IL11, and HBEGF mRNA in human astrocytes by FTY-P was confirmed in independent experiments on primary astrocytes and human astrocytoma cells by qPCR." (PMID 26419927, 2015).